CD276 (CD276 molecule)
Diseases named in the same sentence as CD276 in open-access papers (continued):
Sharing a sentence is not in itself a finding about the gene and the disease.
ovarian carcinoma (62 papers, 2013 to 2025). A malignant neoplasm originating from the surface ovarian epithelium. "B7-H3 (CD276) is an immunoregulatory molecule of the B7 family, minimally expressed in normal tissues but highly overexpressed in many solid tumors, including ovarian cancer." (PMID 40940995, 2025). "CD276 Dash CAR-T also showed greater cytotoxicity in rechallenge of ovarian cancer cell SKOV3 at a lower 1:9 and 1:27 E: T ratios." (PMID 38978106, 2024). "MAb 376.96 is another anti-CD276 monoclonal antibody that recognizes the expression of CD276 epitopes on differentiated ovarian cancer cells and chemotherapy-resistant cancer cells." (PMID 33842369, 2021). "Among the potential ADC targets in ovarian cancer, the immune checkpoint molecules B7-H3 (also known as CD276) and B7-H4 (also referred to as VTCN1, B7x, or B7S1) have emerged as particularly promising due to their overexpression in ovarian tumors and their role in immune evasion." (PMID 41357243, 2025). "However, an increasing number of studies have shown that CD276 was frequently overexpressed in tumor cells and tumor vessels of human lung, breast, colon, endometrial, renal, and ovarian cancer." (PMID 39766794, 2024). "CD276 was also evaluated in relation to its involvement in the development of ovarian cancer." (PMID 37373167, 2023). "Additionally, CD276 also inhibits tumor growth in ovarian cancer via activating the PI3K/AKT signaling pathway through the upregulation of BCL-2, which is related to chemoresistance." (PMID 36358792, 2022). "B7-H3, also known as CD276, is an immune checkpoint protein that is overexpressed in various types of cancers, including breast, lung, and ovarian cancers." (PMID 38727261, 2024). "MSLN was positively correlated with immunosuppressive genes in ovarian cancer, such as LGALS9, CD276, TMIGD2, CD200, TNFRSF14, and human leukocyte antigen (HLA)-related families including HLA-DRA, HLA-DRB1, HLA-DPA1, HLA-DMA, HLA-E, etc.." (PMID 35692779, 2022). "CD276 is a type I transmembrane protein with two extracellular IgC and variable (IgV) domains, mainly expressed on tumor cells, including breast cancer, renal cell carcinoma, NSCLC, endometrial cancer, and ovarian cancer cells." (PMID 36358792, 2022). "The dual blockade of PD-1 and CTLA-4, conducted to simultaneously inhibit CD276, can help in inhibiting the activation of T cells and cytokine secretion, thereby also downregulating LAG-3 expression and improving antitumor immunity to achieve inhibition of ovarian cancer metastasis." (PMID 34367975, 2021).
gastric cancer (56 papers, 2009 to 2026). A primary or metastatic malignant neoplasm involving the stomach. "Meanwhile, the positive correlation between CD276 mRNA expression and the number of circulating tumor cells was observed in blood specimens of gastric cancer patients." (PMID 33932112, 2021). "In many cancer entities including pancreatic, hepatic and gastric cancers, B7-H3 (CD276) is overexpressed on tumor cells and also on the tumor vasculature, the latter allowing for improved access of immune effector cells into the tumor site upon therapeutic targeting." (PMID 37122707, 2023). "The RT-PCR fold-change data from this study provide an overview of B7-H3 (CD276) and CD155 (PVR) gene expression in gastric cancer." (PMID 41225987, 2025). "Other studies have shown that gastric cancer-derived MSCs activate the AKT/c-Myc/mTOR pathway in gastric cell lines and upregulate CD276 expression, thereby promoting the migration of gastric cancer cells." (PMID 39679363, 2024).
hepatocellular carcinoma (50 papers, 2011 to 2025). A malignant tumor that arises from hepatocytes. "The metalloproteinase CD156c and the immune checkpoint molecule CD276 are additional antigens whose expression is shared by fetal hepatoblasts and hepatocellular carcinomas." (PMID 36845728, 2023). "CD276 mainly regulates the proliferation of oral cancer, hepatocellular carcinoma, colorectal cancer, hematologic tumor, gynecological oncology, and lung adenocarcinoma." (PMID 36358792, 2022). "The combination of vasodilator and CD276-pcDNA3.1 inhibits tumor angiogenesis and promotes leukocyte infiltration in hepatocellular carcinoma (HCC)." (PMID 33842369, 2021). "In addition, CD276 (B7-H3), a newly identified immunomodulatory protein, also has a strong immunosuppressive effect and also promotes vasculogenic mimicry formation in the hepatocellular carcinoma microenvironment." (PMID 37059591, 2023). "Similarly, high expression of OX40, CD276, CTLA4 was significantly associated with poor prognosis of hepatocellular carcinoma." (PMID 34869039, 2021). "Due to the importance of ICI in the immunotherapy of hepatocellular carcinoma, we further analyzed the differential expression of immune checkpoint genes between the two groups, and found that the expression in the low-risk group is higher, while the results for TNFSF4 and CD276 are the opposite." (PMID 36672493, 2023). "To investigate the role of PD-L1, CD4, CD8, CD276 and SOCS3 in Hepatocellular Carcinoma, we processed GSE102079 and GSE121248 datasets from Gene Expression Omnibus (GEO)." (PMID 32742491, 2020). "Consistent with the functions of CD276 in CRC and hepatocellular carcinoma, knockdown of CD276 resulted in growth arrest as evidenced by reduced cell viability and increased cell apoptosis." (PMID 27329595, 2016). "Hence, we retrospectively selected 74 hepatocellular carcinoma cases and performed immunohistochemical analysis for PD-L1, CD4, CD8, CD276 and SOCS3 for each paraffin-embedded block." (PMID 32742491, 2020).
medulloblastoma (41 papers, 2008 to 2026). A malignant, invasive embryonal neoplasm arising from the cerebellum. "Moreover, we recently reported that high CD276 mRNA levels are associated with the B7‐H3 protein levels, unfavorable outcomes, and metastasis in patients with medulloblastomas." (PMID 40880425, 2025). "Based on these results, CD276 (B7-H3) is a strong candidate for future blockade approaches in medulloblastoma." (PMID 36825029, 2023). "We further assessed the association of CD276, CD47, CD24, and PVR expression profiles by nCounter and patient survival analysis in the 80 medulloblastomas Brazilian cohort." (PMID 36825029, 2023). "The results showed that the anti-CD276 antibody-installed PIC/m improved intracellular delivery into CD276-expressing medulloblastoma cells in a CD276-dependent manner." (PMID 37050422, 2023). "Our results are similar to studies that measured the levels of CD276 expression in different brain tumors, including in medulloblastoma samples and cell lines." (PMID 36825029, 2023). "Herein, we focused on the possibility of targeting CD276/B7-H3, which is highly expressed on the medulloblastoma cell membrane, as a strategy for enhancing the cellular uptake of ligand-installed nanocarriers." (PMID 37050422, 2023). "Importantly, the analysis revealed overexpression of CD24 and CD276, which can constitute prognostic biomarkers and attractive immunotherapy targets for medulloblastomas." (PMID 36825029, 2023). "Silencing miR-1253 targets CDK6 and CD276 to suppress the growth of medulloblastoma." (PMID 35464451, 2022). "We investigated the clinicopathological and prognostic relevance of the immune checkpoint molecules B7-H3 (CD276) and CD47 in medulloblastoma." (PMID 42196785, 2026). "Among the 19 immune checkpoint-related genes evaluated by nCounter in the Brazilian series of medulloblastomas, we found increased mRNA counts of CD24, CD276, CD47, and PVR (CD155)." (PMID 36825029, 2023). "High expressions of CDK6 and CD276 have a negative influence on medulloblastoma survival, meaning that they play pro-oncogenic roles in medulloblastoma, supporting similar findings from prior studies." (PMID 35464451, 2022). "Moreover, it confirmed the overexpression of CD24 and CD276 in medulloblastomas compared with the non-tumor tissue." (PMID 36825029, 2023). "Altogether, CD276 and CD24 are the most attractive immune checkpoints to be targeted in medulloblastoma, given their higher expression in tumors than in non-tumor tissue and their association with worse prognosis." (PMID 36825029, 2023).
brain tumors (39 papers, 2020 to 2026). "We found that genes responsible for GD2 synthesis (B4GALNT1 and ST8SIA1) and CD276, encoding B7-H3, were expressed at similar or lower levels in MB than in other brain tumors." (PMID 41159102, 2025). "A CD276 CAR T cell clinical trial has opened specifically targeting a range of pediatric brain tumors including DIPG (NCT04185038) and early safety studies have shown good clinical tolerance even after 40 infusions icv." (PMID 37152812, 2023). "In this study, an anti-CD276 antibody was introduced to the N3-PIC/m surface to enhance the delivery efficiency to pediatric brain tumor cells." (PMID 37050422, 2023). "B7-H3 (CD276) is a checkpoint molecule that binds to brain tumours and is a potential target for GBM." (PMID 35454848, 2022). "The role of CD276 in brain tumors has been recently reviewed." (PMID 40801642, 2025). "Future studies are needed to explore whether CD24, CD47, or CD276 (B7H3) inhibitors would constitute alternative immunotherapy approaches in CMMRD‐derived brain tumors." (PMID 40880425, 2025). "The co-inhibitory immune checkpoint B7 homolog 3 (B7-H3, CD276), with an unknown receptor, may also be involved in the immune evasion of brain tumors and, to an extent, MB." (PMID 34771550, 2021). "The B7-H3 (known also as CD276), a transmembrane checkpoint protein overexpressed in several cancers including pediatric solid tumors is another target for brain tumors CAR-T therapy." (PMID 36983330, 2023). "Analysis of the cell surfaceome in pediatric and adult tumors revealed EphA3 as a prominent cell surface protein across various brain tumor subtypes, especially in the context of comparison to existing immunotherapeutic targets in clinical development EphA2, HER2, CD276, CD70, and EGFR." (PMID 39111833, 2024).
colon carcinoma (35 papers, 2009 to 2026). "Accordingly, the exploration on the role of CD276 in colon cancer has dual potential of prognostic prediction and therapeutic target for clinical application." (PMID 38260829, 2023). "Here, the immune gene CD34/CD276 with different m6A peak was obtained by m6A sequencing (MeRIP-seq) of colon cancer (CRC)clinical samples and combined with MsIgDB database, which was used to perform cluster analysis on TCGA-COAD level 3 data." (PMID 34307389, 2021). "In contrast, CD27, CD276, LAG3, LGALS9, PDCD1, and TMIGD2 showed a highly enriched trend of expression with RFX1 in colon cancer." (PMID 41425715, 2025). "On account of CD276 has just been identified as a potential biomarker in colon cancer recently and has not yet become part of routine clinical application, there is certain difficulty to establish a large database that integrate CD276 expression and H&E-stained images." (PMID 38260829, 2023).
lung adenocarcinoma (33 papers, 2018 to 2025). A carcinoma that arises from the lung and is characterized by the presence of malignant glandular epithelial cells. "Usually, the expression of CD276 in patients with lung adenocarcinoma or smoking history is associated with a shorter overall survival." (PMID 34917619, 2021). "Furthermore, high CD276 expression was associated with a twofold increased risk of death, confirming its potential prognostic role in lung adenocarcinoma." (PMID 40821788, 2025). "For lung adenocarcinoma, survival analysis revealed a significant difference between high and low CD276 expression groups." (PMID 40821788, 2025). "This suggests that in the future, we can combine IGSF10 restoration strategies with CD47/CD276 blockade to inhibit the progression of lung adenocarcinoma." (PMID 41447338, 2025). "Using survival data derived from UCSC Xena based on the TCGA datasets, we evaluated the impact of CD276 expression levels on overall survival (OS) in patients with lung adenocarcinoma and lung squamous cell carcinoma by Kaplan-Meier survival analysis." (PMID 40821788, 2025). "In this context, we identified the hsa-miR-150-5p/CD276 ratio as one of the most prognostic in lung adenocarcinoma (TCGA-LUAD), whereby hsa-miR-150-5p is targeting CD276 (also known as B7-H3) and is inversely associated with overall survival (Use Case S2)." (PMID 35642895, 2022). "have reported that CD276 is overexpressed in lung adenocarcinoma and is associated with lymph node and distant metastases, and CD276 expression can promote EMT of lung adenocarcinoma cells and facilitate tumor infiltration and metastasis." (PMID 34367975, 2021).
lymph node metastasis (33 papers, 2009 to 2025). "In NSCLC, a previous meta-analysis found that the high expression of CD276 was significantly associated with patients’ lymph node metastasis and advanced TNM staging." (PMID 34917619, 2021). "In histological examinations of patients with NSCLC, CD276 expression was significantly associated with NSCLC lymph node metastasis and advanced TNM stage, and CD276 was found to have an inhibitory effect on the immune system of NSCLC." (PMID 31737785, 2019). "However, there are also statistics showing that abnormal expression of CD276 is associated with lymph node metastasis and late stage of NSCLC in TNM stage." (PMID 31737785, 2019). "In OSCC and HNSCC, higher ICOS or lower CD276/ICOS is a good prognostic marker for patient survival and lymph node metastasis." (PMID 39104717, 2024). "However, our analysis using Cox regression showed that lymph node metastasis, rather than CD276 expression, was an independent prognostic predictor for ESCC patients after surgery." (PMID 38566988, 2024).
head and neck squamous cell carcinoma (32 papers, 2016 to 2025). A squamous cell carcinoma that arises from any of the following anatomic sites: lip and oral cavity, nasal cavity, paranasal sinuses, pharynx, larynx, and salivary glands. "A recently published study showed that CD276 is highly expressed by cancer stem cells (CSCs) in mouse and human head and neck squamous cell carcinoma, thereby facilitating immune escape and promoting tumor growth and lymph node metastasis." (PMID 36717836, 2023). "Coincidentally, some head and neck squamous cell carcinoma stem cells especially upregulated CD276 to evade host immune responses provoked by CD8+ T cells." (PMID 36494785, 2022). "A blockade of CD276 (B7-H3) checkpoint molecules on the surface of human head and neck squamous cell carcinoma (HNSCC) CSCs provided T-cell-dependent elimination of these cells, inhibiting tumor growth and metastasis formation in the HNSCC mouse model in vivo." (PMID 36613838, 2022). "Cancer stem cells of head and neck squamous cell carcinoma upregulated CD276 to evade host immune responses of CD8+ T cells." (PMID 36494785, 2022). "In addition, a recent study indicates that CD276 facilitates evasion of immune surveillance at various stages of cancer, including initiation, development, and metastasis of head and neck squamous cell carcinoma." (PMID 38637557, 2024).
sarcoma (31 papers, 2019 to 2026). A usually aggressive malignant neoplasm of the soft tissue or bone. "Targeting protein B7-H3 (CD276) in cancer cells at the genomic level or PD-L1 with antibodies in a sarcoma model, resulted in decreased glycolysis and glucose consumption both in vitro and in vivo." (PMID 33608051, 2021). "B7-H3 (CD276) CAR T cells are also being tested for the treatment of pediatric sarcomas." (PMID 34572932, 2021). "However, several pan-cancer immunotherapy target antigens, including B7-H3/CD276, GD2 and Erbb2/HER2/neu were markedly upregulated in sarcoma GEMMs." (PMID 40523919, 2025). "With regard to NK cells and their role in ADCC, Enoblituzumab is a fully humanized Fc-optimized antibody against B7-H3 that is expressed on a wide range of solid tumors including sarcomas and is currently being studied in patients with CD276+ tumors, including sarcomas." (PMID 31502008, 2019).
renal cell carcinoma (26 papers, 2010 to 2025). "The same Fc motif was applied to the MGA271 mAb (anti-CD276), which targets B7-H3+ tumor cells and resulted in an increased binding to FcγRIIIa, enhanced ADCC, and potent antitumor activity in a renal cell carcinoma/bladder cancer xenograft mouse model." (PMID 28018347, 2016).